SEMA3F (semaphorin 3F)
Diseases named in the same sentence as SEMA3F in open-access papers (continued):
Sharing a sentence is not in itself a finding about the gene and the disease.
esophageal adenocarcinoma (1 paper, 2024). A malignant tumor with glandular differentiation arising predominantly from Barrett mucosa in the lower third of the esophagus. "In summary, our study has identified SEMA3F as a factor associated with favorable patient survival, particularly in those with early-stage esophageal adenocarcinomas." (PMID 39232098, 2024). "We demonstrated that positive SEMA3F protein expression is correlated with favorable patient survival in esophageal adenocarcinoma." (PMID 39232098, 2024). "In summary, SEMA3F emerges as an independent predictor for a favorable prognosis in patients with early-stage esophageal adenocarcinoma." (PMID 39232098, 2024). "In summary, SEMA3F expression could be identified as an independent factor for favorable patient survival in patients with early-stage esophageal adenocarcinoma." (PMID 39232098, 2024). "In this study, we investigated the role of SEMA3F and its receptor, NRP2, in patients diagnosed with esophageal adenocarcinoma." (PMID 39232098, 2024). "We conducted an immunohistochemical evaluation of SEMA3F and NRP2 protein expression in 776 patients with esophageal adenocarcinoma who underwent Ivor-Lewis esophagectomy at the University Hospital of Cologne." (PMID 39232098, 2024). "Hence, the objective of this study was to elucidate the roles of SEMA3F and its receptor NRP2 in esophageal adenocarcinoma." (PMID 39232098, 2024). "The role of SEMA3F and NRP2 in esophageal adenocarcinoma remains unclear." (PMID 39232098, 2024).
gastric cancer (1 paper, 2017). A primary or metastatic malignant neoplasm involving the stomach. "AMPK has been shown to increase the expression of tumor suppressor genes including F-box and WD repeat domain containing 7 (FBXW7), semaphorin III/F (SEMA3F), and p21Cip1 (p21) in gastric cancer cells, and RORα functions a transcription activator." (PMID 28052040, 2017). "Furthermore, AICAR treatment increased RORα recruitment on the promoters of tumor suppressor genes (i.e., FBXM7, SEMA3F and p21) leading to apoptosis in human gastric cancer cells." (PMID 28052040, 2017).
lung injury (1 paper, 2023). "Both SEMA3F and SEMA7A are secreted by activated immune cells and have emerged as regulators of neutrophil migration, vascular permeability and cytoskeletal remodeling, and the initiation of an inflammatory signaling cascade in models of acute lung injury." (PMID 37893159, 2023).
myocardial infarction (1 paper, 2022). Gross necrosis of the myocardium, as a result of interruption of the blood supply to the area, as in coronary thrombosis. "A polymorphism in SEMA3F is associated with myocardial infarction." (PMID 35986301, 2022).
myopia (1 paper, 2019). "Our study identified methylation differences in the semaphorins, such as SEMA3F, SEMA4B, SEMA4C and SEMA5A that were significantly associated with myopia." (PMID 30858441, 2019).
neuroendocrine carcinoma (1 paper, 2015). A malignant neuroendocrine neoplasm composed of cells containing secretory granules that stain positive for NSE and chromogranin. "We also demonstrated that overexpression of SEMA3F reduced the proliferation of neuroendocrine cancer cells in vitro, in association with growth inhibition of the xenografted tumors in vivo." (PMID 26447612, 2015).
neuroendocrine tumors (1 paper, 2015). "We then addressed the mechanisms responsible for SEMA3F loss of expression in neuroendocrine tumor cells." (PMID 26447612, 2015). "In summary, we have showed for the first time that the axon guidance factor SEMA3F was expressed in endocrine cells of the intestinal epithelium and was lost in neuroendocrine tumors arising in the distal small intestine, according to the stage." (PMID 26447612, 2015). "In two different in vivo experimental models, we observed a significant anti-tumoral effect of the re-expression of SEMA3F in STC-1 neuroendocrine tumor cells." (PMID 26447612, 2015). "Therefore, SEMA3F and its signaling pathway could represent a target for neuroendocrine tumor therapy." (PMID 26447612, 2015). "We first aimed to determine the expression profiles of SEMA3F and its preferential receptor NRP-2 in several neuroendocrine tumor cell lines." (PMID 26447612, 2015). "In our context, SEMA3F could slow proliferation by reducing the activity of mTOR and MAPK pathways, demonstrated to be up-regulated in several cancer types, including neuroendocrine tumors." (PMID 26447612, 2015).
Sepsis (1 paper, 2024). Sepsis is defined as life-threatening organ dysfunction caused by a dysregulated host response to infection. "In conclusion, we have shown that patients with sepsis have different serum concentrations of SEMA3A, SEMA3C, SEMA3F, SEMA4D, and SEMA7A compared to healthy controls and that their kinetics during sepsis correlate with disease severity and outcomes." (PMID 39770766, 2024). "While SEMA3A was decreased, SEMA3C, SEMA3F, SEMA4D, and SEMA7A were increased in sepsis patients, and all analyzed SEMA showed good accuracy in identifying patients with sepsis." (PMID 39770766, 2024). "Patients with sepsis had significantly higher serum levels of SEMA3C, SEMA3F, SEMA4D, and SEMA7A and a significantly lower SEMA3A." (PMID 39770766, 2024). "While SEMA3A was decreased, SEMA3C, SEMA3F, SEMA4D, and SEMA7A were increased in sepsis patients." (PMID 39770766, 2024).
squamous cell carcinoma (1 paper, 2022). A carcinoma arising from squamous epithelial cells. "We analyzed the transcriptional expression of SEMA3F and NRP2 in a cohort of 53 patients with cN0 squamous cell carcinoma treated with an elective neck dissection." (PMID 35565388, 2022).
streptococcal pneumonia (1 paper, 2020). A febrile disease caused by streptococcus pneumoniae. "Importantly, neutrophils deficient in Sema3f were able to mount an antimicrobial response that was sufficient to control bacterial numbers where animals were exposed to a bacteremic model of streptococcal pneumonia." (PMID 32191647, 2020).
ZIKV infection (1 paper, 2024). "Further, SEMA3C and SEMA3F, two members of the semaphorin class 3 family of neuronal guidance genes, were also downregulated at the 48 hpi timepoint in ZIKV infection, suggesting that ZIKV infection may reduce neuronal maturation or synapse formation." (PMID 38440980, 2024).
tumor (73 papers, 2008 to 2026). "SEMA3F has been implicated in immune signaling and immune synapse formation, and in regulating the localization and retention of tumor-associated macrophages." (PMID 38895099, 2024). "Conversely, high expression of SEMA3F has been associated with a reduction in the degree of tumor lymphovascular infiltration and increased survival." (PMID 35565388, 2022). "In a study of 101 SI-NETs, the gene SEMA3F, which encodes for semaphorin 3, was observed to be methylated in 50% of tumours and correlated with a higher Ki67 and tumour stage, an observation which warrants further investigation." (PMID 34439335, 2021). "The SEMA3F-NRP pathway generally also opposes VEGF activity in tumor models, where a loss of SEMA3F leads to gross vessel overgrowth." (PMID 34424892, 2021). "SEMA3F is the only family member whose expression is consistently increased in primary tumour samples as compared to the associated adjacent normal." (PMID 32241267, 2020). "SEMA3C is frequently associated with invasion and metastasis, while SEMA3F was mainly reported to function as a tumour suppressor." (PMID 32241267, 2020). "A single intravenous injection of adenovirus encoding human Sema3F produced comparable effects on the vasculature of pre-implanted U87MG tumor cells." (PMID 31052281, 2019). "In association with an inhibition of tumor growth, Sema3F overexpression in subcutaneously injected U87MG cells led to a striking perturbation of angiogenesis, characterized by constricted vessels with collapsed lumens." (PMID 31052281, 2019). "In this review, we discuss the novel molecular mechanisms underlying SEMA3F activity in vascular and tumor biology." (PMID 30532711, 2018). "Previous studies in other tumor types have shown that SEMA3F expression is associated with a reduction in activated MAPK signaling." (PMID 26447612, 2015). "The functional effects of the compounds were correlated with the induction of expression of the usual HDACi target TSG p21, E-cadherin, Bim and Sema3F, implicated in control of the cell cycle, apoptosis and tumor progression." (PMID 24980825, 2014). "We also examined the effects of sema3A and sema3F expression on the concentration of tumor associated blood vessels in MCF-7 cells." (PMID 18818766, 2008). "Furthermore, SEMA3F and its associated pathways should be explored as potential tumor-suppressing agents." (PMID 39232098, 2024). "In addition to the increased risk of lymphatic metastasis, high NRP2 and low SEMA3F expression has been associated with an increase in tumor aggressiveness, evidenced as an increase in the capacity for proliferation and infiltration." (PMID 35565388, 2022). "In summary, our results indicate that SEMA3A, SEMA3C, SEMA3E, and SEMA3F are more often to promote tumorigenesis and associate with poor prognosis, while the other SEMA3s are more often to play a tumour suppressor role and generally associate with better prognosis." (PMID 32241267, 2020). "Correspondingly, tumor-associated target genes including ALDH3A2, SEMA3F, MAP4K5, and TRIP13 were upregulated, whereas PIK3IP1, AGO2, MMP2, and RALBP1 were suppressed." (PMID 41897301, 2026). "Sema3B and Sema3F act as tumor suppressors in some cancers by suppressing tumorigenesis in certain adenocarcinoma cell lines." (PMID 40277760, 2025). "One of these ligands, SEMA3F exhibits well-documented tumor-suppressive activities mediated through NRP2 and plexinA1 (PLXNA1)." (PMID 41391772, 2025). "SEMA3A and SEMA3F function as tumor suppressors, inhibiting neural invasion, angiogenesis, and metastasis by antagonizing neuropilin/plexin signaling." (PMID 41009819, 2025).
tumor (continued). "Sema3F and Sema3B act as tumor suppressors, whereas Sema3F and Sema3B are involved in cancer progression." (PMID 40277760, 2025). "The effects of SEMA3F are likely due to its autocrine/paracrine effects on both epithelial and myoepithelial cells, with the latter playing a key role as a tumor suppressor in BC." (PMID 39138514, 2024). "In subgroup analyses of patients with early tumor stage (pT1N0-3, pT1-4N0, pT1N0), positive SEMA3F expression correlated with better patient survival." (PMID 39232098, 2024). "SEMA3F was first described as a repulsive axonal guidance signal and is involved in cancer-related vascular and tumor biology as a PI3K-AKT-mTOR pathway inhibitor." (PMID 39138514, 2024). "Sema3F is a potent inhibitor of tumor angiogenesis and metastasis where it inactivates RhoA, depolymerizes F-actin, and suppresses tumor cell migration." (PMID 38592275, 2024). "Sema3F is an inhibitor of tumor angiogenesis and tumor lymph angiogenesis and inhibits lymph vessels-mediated metastasis of head and neck squamous carcinoma cells." (PMID 37627074, 2023). "Several class-3 semaphorins such as sema3A, sema3B and sema3F have been found to function as potent inhibitors of tumor angiogenesis and consequently as inhibitors of tumor progression." (PMID 36658114, 2023). "Several semaphorins including Sema3a, Sema3f, Sema3g and Sema6a have been reported to exert tumor growth-inhibiting activities while several others such as Sema4d and Sema6d have been associated with tumor-promoting functions in various cancer types." (PMID 35223842, 2022). "NRP2, which encodes the neuropilin-2 receptor that is repressed by hypoxia and regulates both VEGF and SEMA3F activity to induce tumor angiogenesis, also exhibited DGE with two DE transcripts and one transcript with changing proportions." (PMID 35562897, 2022). "IHC analysis demonstrated that SEMA3F overexpression decreased tumor weight and number of CD31+ cells in comparing with control mice." (PMID 34209679, 2021). "In lung cancer, a loss of two chromosome regions containing semaphorins 3p21.3 (SEMA3B and SEMA3F) and 5q21–22 (SEMA6A) is associated with the inhibition of proliferation and invasion of tumor cells and angiogenesis." (PMID 34209679, 2021). "After the regulatory effect of FAM83C-AS1 in CRC tumor cells was studied in vitro, in vivo assays were successively conducted, which further manifested that FAM83C-AS1 contributed to CRC tumor growth and metastasis by inhibiting SEMA3F expression." (PMID 33109776, 2020). "In general, our results show that SEMA3A, SEMA3C, and SEMA3F are primarily upregulated in cancer cells, while the rest of SEMA3s are mainly down-regulated in the tested tumours." (PMID 32241267, 2020). "Both in vitro and in vivo rescue assays exhibit that SEMA3F is dispensable for the tumor-promoting effects of FAM83C-AS1 on CRC progression." (PMID 33109776, 2020). "Among the tumor specimens with IDH mutation, mRNA levels of SEMA3B, SEMA3C, SEMA3D, SEMA3G, NRP2, PLXNA2, and CDH1 were significantly higher (p < 0.05), while SEMA3F, NRP1, ITGB3, ITGA5, and VEGFA genes were under-expressed (p < 0.05)." (PMID 33036421, 2020). "Patient age, tumor grade, status of IDH mutation and expression of seven genes (SEMA3A, SEMA3D, SEMA3F, SEMA3G, ITGB3, ITGA5, and VEGFA) significantly correlated with patient OS (p < 0.05)." (PMID 33036421, 2020). "Whereas SEMA3A, SEMA3C, and SEMA3F were mainly up-regulated in the tested tumours, the rest of the members SEMA3B, SEMA3D, SEMA3E and SEMA3G were primarily down-regulated with a few exceptions." (PMID 32241267, 2020). "SEMA3F is a potent inhibitor of metastasis, and, therefore, its repression enhances tumor dissemination." (PMID 33081056, 2020). "For instance, while SEMA3A binds specifically to NRP1 and SEMA3F binds to NRP2-containing holoreceptors to promote tumor cell normalization and inhibit metastasis in endothelial cells, SEMA3C shows similar affinities for NRP1 and NRP2." (PMID 32640719, 2020).
tumor (continued). "In the current study, we demonstrate that FAM83C-AS1 transcriptionally regulate SEMA3F expression in CRC tumor cells." (PMID 33109776, 2020). "Although SEMA3F has been reported to have inhibitory effect on CRC tumor cell proliferation, metastasis and stemness, knowledge of the regulatory mechanism behind SEMA3F expression in CRC remains extremely limited." (PMID 33109776, 2020). "Based on the results obtained from this study, lncRNA FAM83C antisense RNA 1 (FAM83C-AS1) was found to be highly expressed and negatively correlated with SEMA3F in CRC tumor tissues and cells." (PMID 33109776, 2020). "This tumor-suppressing effect induced by either local or systemic administration of Sema3F was attributed to Sema3F/NRP2-mediated inhibition of Akt-mTOR signaling." (PMID 31052281, 2019). "Taken together, these experiments indicate that sema3F can directly affect the behavior of tumor cells that express appropriate sema3F receptors." (PMID 30696103, 2019). "Sema3A, Sema3B and Sema3F have been long considered inhibitors of tumor growth and metastasis, even if it has been reported that Sema3E inhibits tumor growth but promotes metastasis." (PMID 30454024, 2018). "SEMA3F has therapeutic potential, not only in tumor biology, but also to target immune-related diseases such as allograft rejection." (PMID 30532711, 2018). "SEMA3B and SEMA3F have been implicated in mediating tumor-suppressing effects, whereas VEGFA has been shown to promote tumor cell proliferation and survival by binding to NRP127–33." (PMID 29018205, 2017). "This study revealed that SEMA3F plays a role as a tumor suppressor in OSCC cell proliferation, migration and invasion." (PMID 29299034, 2017). "To better understand the tumor suppressive effect of SEMA3F in oral tumorigenesis, we identified the function of SEMA3F in SAS and HSC2 cell lines using transwell analysis." (PMID 29299034, 2017). "For example, SEMA3F can act as a functional inhibitor of tumor cell growth, metastasis and tumor angiogenesis." (PMID 26319580, 2015). "Our findings suggest that SEMA3F has therapeutic potential, not only in tumor biology, but also for instance to target chronic immune-mediated diseases, allograft rejection and/or angiogenesis related pathology." (PMID 26156437, 2015). "We then explored the possible relation between SEMA3F expression and tumor cell proliferation, as assessed by Ki67 values determined by counting positive cells in areas of highest density of labeled cells." (PMID 26447612, 2015). "Here, we show through clinical and experimental in vitro and in vivo approaches, that SEMA3F expression decreases with tumor progression in human ileal NETs and that this molecule is a negative regulator of neuroendocrine cell proliferation." (PMID 26447612, 2015). "In these studies, we used an adenovirus to evaluate the effects of high levels of circulating SEMA3F protein on tumor growth and angiogenesis after tumors have developed." (PMID 26156437, 2015). "Combined, SEMA3F/NRP2 signaling represents an important regulatory axis in tumor lymphangiogenesis, thus providing new therapeutic targets to halt aggressive metastasis." (PMID 26319580, 2015). "In one approach, parental U87MG cells or U87MG cells that were engineered to constitutively overexpress SEMA3F were implanted subcutaneously into nude mice (1 × 106/mouse); tumor size (mm3) was measured at the indicated time points over a period of 3 weeks." (PMID 26156437, 2015). "The regulation of mTOR by SEMA3F was found in several cell types, including T cells, endothelial cells and tumor cell lines, all of which are well established to utilize this signaling pathway for cellular activation, differentiation and proliferation." (PMID 26156437, 2015). "Taken together, our results suggested that SEMA3F decreased tumor growth through several mechanisms targeting cell proliferation and survival." (PMID 26447612, 2015).